GRP (gastrin releasing peptide)
Diseases named in the same sentence as GRP in open-access papers (continued):
Sharing a sentence is not in itself a finding about the gene and the disease.
prostate carcinoma (26 papers, 2009 to 2025). A carcinoma that arises from epithelial cells of the prostate gland. "GRPR is also associated with the growth of human prostate carcinoma and pancreatic cancer by an autocrine loop with gastrin-releasing peptide (GRP)." (PMID 35744904, 2022). "Therefore, GRPR expression has traditionally been associated with low-grade disease, as various GRP agonist and antagonist radioligands have shown promising results in the detection of early-stage prostate cancer." (PMID 39598482, 2024). "In this study, we have developed iron oxide nanoparticles (IONs) functionalized with the Prostate Specific Membrane Antigen (PSMA) and Gastrin Releasing Peptide (GRP) ligands for dual targeting of Prostate cancer." (PMID 39380961, 2023). "The majority of human prostate cancers express bombesin/GRP receptors, implying that GRP‐mediated regulation is involved in PCa progression." (PMID 36470854, 2023). "Recently, elastin-like polypeptide (ELP)-based self-assembling micelles with tethered gastrin-releasing peptide (GRP) on the surface have been suggested to actively target prostate cancer cells." (PMID 35494646, 2022). "In another study, the protein contrast agent ProCA1.GRP contained a fused gastrin-releasing peptide (GRP) for active targeting and imaging of prostate cancer and showed good retention during intra-tumour administration." (PMID 35328725, 2022). "A large amount of data demonstrate neuropeptides, such as gastrin-releasing peptide (GRP), are associated with accelerated prostate cancer progression and inferior prognosis." (PMID 32205838, 2020). "Next we tested if GRP/GRPR signaling has an immediate effect on prostate cancer cells with stem cell-like properties." (PMID 32205838, 2020). "In fact, it has been recently shown that GRPR on prostate cancer cells can be targeted with hybrid elastin-like polypeptide/liposome nanoparticles via a GRP-ELP fusion protein." (PMID 29861840, 2018). "For the first time, in this study we show the role of GABA and GABAB receptor 1 (GABBR1) expression in GRP secretion in NE-like prostate cancer cells." (PMID 29980692, 2018). "Clinical, histological, and experimental observations have implicated GRP and GRPR in the pathophysiology of prostate cancer progression." (PMID 21745389, 2011). "Furthermore, GABA elevation in neuroendocrine-like cells induces the secretion of gastrin-releasing peptides (GRP), promoting the invasive potential of PC-3 prostate cancer cells." (PMID 38287309, 2024). "Gastrin-releasing peptide (GRP) and its receptor (GRPR) have also been linked to cancerous malignancies and GRPR has been shown to induce the release of IL-8 and vascular growth factor in the case in human prostate cancer cell lines." (PMID 34572888, 2021). "Methionine-enkephalin expression in colorectal carcinomas may be associated with nodal and liver metastasis, while expression of bombesin/gastrin-releasing peptide in prostate cancer may be related to the lymph node metastases." (PMID 33672617, 2021). "Thus, the effects of GRP/GRPR signaling abrogation in inhibiting prostate cancer cell tumorigenicity result from diminishing the population of cancer-propagating cells." (PMID 32205838, 2020). "GRP can promote cell proliferation and accelerate migration and invasion of prostate cancer cells." (PMID 32205838, 2020). "In addition, GRP modulates the function of immune cells and, most importantly, it acts as an autocrine growth factor in several tumour types, including lung and prostate cancer." (PMID 30543050, 2018). "Both GRPR and its specific ligand GRP (gastrin-releasing peptide), are known to be overexpressed in several human malignancies, including neuroblastoma, lung, breast, pancreatic, colorectal, gastric, esophageal and prostatic cancer." (PMID 26097883, 2015).
prostate carcinoma (continued). "Additionally, FAK has also been established as a significant component in the BBS signaling pathways in prostate cancer and described to play a critical role in GRP-mediated morphogenesis of colon cancer." (PMID 23211542, 2012). "Moreover, GRP activates nuclear factor kappa B-dependent pathway to modulate the expressions of interleukin-8 and vascular endothelial growth factor in prostate cancer cells." (PMID 19169356, 2009). "Moreover, in the prostate carcinoma PC-3 cell model, the action of the gastrin releasing peptide (GRP) analog, bombesin (BN), on the activation of focal adhesion kinase (FAK) and its invasiveness suggests that this kinase might favor metastasis (Lacoste, Aprikian & Chevalier, 2005)." (PMID 32266115, 2020). "Proof of concept for this has already been provided in our earlier work, when the N-terminal amino acid of GRP (neuromedin C) was successfully fused to ELP micelles and increased uptake into prostate cancer cells demonstrated." (PMID 29861840, 2018). "GRP and GRPR are expressed by NE cells in prostate cancer tissue and by prostate cancer-derived cell lines; BBS stimulates the growth of both orthotopic and ectopic prostate cancer cell xenografts in athymic nude mice through GRPR-mediated mechanisms." (PMID 21745389, 2011). "It has also been observed that GABA could induce gastrin-releasing peptide (GRP) secretion via GABBR1, which in turn promotes prostate cancer invasion and migration." (PMID 40900801, 2025). "In sum, our study provides a definitive proof of tumor-suppressive role of MME, links GRP/GRPR signaling to the control of prostate stem/progenitor cells, and shows how dysregulation of such signaling may promote formation of castration-resistant prostate carcinomas." (PMID 32205838, 2020). "Although the aberrant overexpression of COX-2, the BBS-like peptide, GRP, and GRPR has been documented for prostate cancers with NE features, particularly in the setting of recurrent disease, a mechanistic link between GRPR activation and COX-2 expression in prostate cancer cells has not been made." (PMID 21745389, 2011).
itch (19 papers, 2011 to 2025). "Moreover, Tirado-Sánchez showed that GRP is correlated with pruritus severity and is implicated in the pathological mechanism underlying AD." (PMID 34925005, 2021). "Recently, the sensitive skin, a syndrome associated with pruritus, has been characterized as a small fiber neuropathy while, in atopic dermatitis (AD) and psoriasis, two pruritic dermatoses, an increase of GRP+, SP+, VIP+, and CGRP+ cutaneous fiber nerves has been clearly demonstrated." (PMID 34923994, 2021). "Beyond the direct involvement of GRP in the generation of pruritus it may render the spinal cord more susceptible for evoked pruritus: in particular acute electrical stimulation may provoke mainly pain in healthy volunteers." (PMID 33791328, 2021). "In another study, chronic itch caused by IL-33/ST2 was mediated by astrocytic JAK2-STAT3 cascades, which stimulated TNF- to sensitize gastrin-releasing peptide GRPR signaling." (PMID 36983094, 2023). "A study demonstrated that levels of GRP expression in the skin of AD patients were related to the severity of AD and pruritus intensity." (PMID 36983094, 2023). "The optogenic activation of GRP expressing cutaneous sensory fibers resulted in itch behavior, and chemically induced itch was attenuated by conditional deletion of GRP from DRG neurons." (PMID 35321329, 2022). "BNP-NPRA signaling was initially proposed as an itch-specific pathway responsible for transmitting both histamine- and CQ-evoked itch that acts upstream of GRP-GRPR signaling." (PMID 34919054, 2021). "Enhanced expression in the skin and serum levels of GRP and correlation with pruritus and severity in patients with AD have been reported." (PMID 34281281, 2021). "Behavioral evidence using NC/Nga mice suggested that STAT3-dependent spinal cord central sensitization occurs via amplification of GRP signalling under chronic itch conditions." (PMID 35095512, 2021). "GRP and SP are crucially involved in histamine-dependent itch neurotransmission; furthermore, GRP upregulation has been presented in both chronic dermatitis and pruritus mice, which suggests that GRP-expressing nerves have a vital role in mediating pruritus." (PMID 34925005, 2021). "To further investigate the anti-pruritus mechanisms underlying HLJDT, we analyzed pruritus-related markers (i.e., JAK1, HRH4, IL-4αR, GRP, SP, and TRPV-1) from the dorsal root ganglion." (PMID 34925005, 2021). "They found that pruritogens induced Ca2+ responses in GRP+ sensory neurons and that optogenetic activation of GRP+ sensory neurons elicited itch‐related scratching behavior." (PMID 34000759, 2021). "The GRP/GRPR system in the dorsal horn is suggested as a key component of a neuronal network that transmits itch-related information." (PMID 31719558, 2019). "The social transfer of itch through visual information was further demonstrated to be mediated by a neural circuit in the SCN through gastrin-releasing peptide (GRP)-GRP receptor signaling." (PMID 28979194, 2017). "Intriguingly, recent insights further reveal a critical intersection of this system with pruritus: opioid drugs induce itch by suppressing the gating of GRP+ neurons by NPY+ neurons, thereby disinhibiting the GRP-GRPR itch circuit—a disruption that directly triggers pruritic responses." (PMID 41248150, 2025). "Moreover, murine GRP-GRPR signaling is important for the development of contact dermatitis-induced itch." (PMID 34919054, 2021). "Similarly, activation of GRP+ neurons in the spinal cord via ChR2 revealed that burst firing within these neurons is required to induce itch-related behaviors in vivo, providing evidence that a buildup of GRP neuron activity is required for itch." (PMID 32595458, 2020). "As most forms of itch involve a prolonged presence of the pruritic stimulus and sustained activation of pruritoceptors, we first tested whether GRP neurons would be able to sustain repeated burst-like activity over prolonged periods of time." (PMID 31103358, 2019).
itch (continued). "A role for GRP-expressing interneurons in chloroquine-evoked itch?" (PMID 27270268, 2016). "Thus, we propose that NMB and GRP may transmit discrete itch information and NMBR neurons are an integral part of neural circuits for itch in the spinal cord." (PMID 29133874, 2017). "Therefore, understanding the anatomical features and electrophysiological property responding to GRP may be one of the key to reveal itch mechanisms in the spinal cord." (PMID 21699733, 2011). "The IL-31-induced pruritus is mediated by NKB and its receptor NK3R, and then by GRP and its receptor GRPR." (PMID 33924978, 2021). "These CNF contain neuropeptides such as substance P (SP), calcitonin gene-related peptide (CGRP), vasoactive intestinal peptide (VIP), and gastrin-releasing peptide (GRP), known to be inducers and potentializers of pruritus." (PMID 34923994, 2021). "Pruritus by histamine and chloroquine is mediated by NPPB and its receptor NPRA, and then by GRP-GRPR signaling." (PMID 33924978, 2021). "However, in chronic itch patients it might also evoke itch suggesting that the spinal cord processing of itch has been facilitated in these patients potentially be previous release of GRP." (PMID 33791328, 2021). "A comparison of MF patients with and without pruritus revealed higher levels of IL-31, substance P, GRP, and CCL24 in the former." (PMID 39068637, 2024). "CQ itch is mediated in part by GRP-GRPR signaling independent of glutamatergic transmission." (PMID 34919054, 2021). "Importantly, GRP‐Gq‐DREADD‐mediated scratching behavior in GRP‐hM3Dq mice was not affected by the ablation of transient receptor potential vanilloid 1+ sensory C‐fibers, and it was also observed to a similar degree under chronic itch conditions." (PMID 34000759, 2021). "Similarly, both GRP and, to a lesser extent, CCL24 (eotaxin-2) were found in higher concentrations in MF patients with current pruritus as compared to those without." (PMID 39068637, 2024). "However, we observed a similar trend in SS, with higher levels of IL-31, GRP, and CCL24 in those with current pruritus compared to those without." (PMID 39068637, 2024).
neuroblastoma (15 papers, 2009 to 2024). Neuroblastoma (NB) is the most common solid, extracranial childhood tumor. "We previously found that the PI3K/AKT signaling pathway is quite active in high-risk neuroblastoma and is regulated by mitogen gastrin-releasing peptide through its G protein-coupled receptor." (PMID 31608140, 2019). "This set of novel observations implicated that PTEN overexpression inhibited GRP-induced neuroblastoma progression." (PMID 24039782, 2013). "Hence, our data indicate that GRP may modulate both the transcription of oncogenes as well as signaling pathways implicated in neuroblastoma progression." (PMID 24039782, 2013). "In contrast, the overexpression of the GRPR in less aggressive SK-N-SH neuroblastoma cells resulted in colony formation, which was inhibited by GRP-blocking antibody." (PMID 34539578, 2021). "Two studies provide evidence for an important role in GRPR activation in neuroblastoma cell lines for the PI-3K pathway in mediating the GRP-stimulated growth effects in these cells." (PMID 34539578, 2021). "This in turn resulted in increased expression and secretion of the proangiogenic factor interleukin-8 (IL-8), suggesting a critical role of this signaling cascade in GRP-induced angiogenesis in neuroblastomas and their development of metastasis." (PMID 34539578, 2021). "In this study in two human neuroblastoma cell lines (JF, SSK-N-SH) in which GRP was silenced using siRNA targeting, there was a marked increase in neuroblastoma cell apoptosis and a decrease in cell proliferation." (PMID 34539578, 2021). "GRP was reported to be involved in the induction of angiogenesis during neuroblastoma progression, which showed up-regulation in AMD in our study." (PMID 28651595, 2017). "Neuroblastoma is a pediatric neuroendocrine tumor that can produce and secrete a variety of neuropeptides, including gastrin-releasing peptide (GRP)." (PMID 23468863, 2013). "Taken together, our results are significant because it identifies a rationale for targeted therapy against GRP to modulate signaling pathways that contribute to neuroblastoma metastasis." (PMID 24039782, 2013). "Taken together, our findings illustrate the significance of GRP in promoting tumor migration, invasion and metastasis and make it a promising target in preventing a more aggressive, malignant neuroblastoma phenotype." (PMID 24039782, 2013). "We also identified PTEN/AKT signaling as a key mediator of the tumorigenic properties of GRP in neuroblastoma cells." (PMID 24039782, 2013). "Most importantly, PTEN overexpression blocked GRP-mediated tumor progression as assessed by in vitro functional assays, thereby, demonstrating the critical role of PTEN in reversing the oncogenic roles of GRP in neuroblastoma." (PMID 24039782, 2013). "Targeted inhibition of GRP decreased the mRNA levels of oncogenes responsible for neuroblastoma progression." (PMID 24039782, 2013). "Here, we demonstrate that GRP silencing decreased the anchorage-independent growth of neuroblastoma cells, which indicates enhanced anoikis-induced cell death in vitro." (PMID 24039782, 2013). "Using a doxycycline inducible system, we demonstrate that GRP silencing decreased anchorage-independent growth, inhibited migration and neuroblastoma cell-mediated angiogenesis in vitro, and suppressed metastasis in vivo." (PMID 24039782, 2013). "While we have demonstrated the importance of GRP in the establishment of neuroblastoma at its primary site, its role in tumor progression and metastasis remains to be fully elucidated." (PMID 24039782, 2013). "We also identified new downstream targets of GRP in neuroblastoma that are known to be responsible for tumor progression." (PMID 24039782, 2013). "We have previously demonstrated the role of gastrin-releasing peptide (GRP) as an autocrine growth factor for neuroblastoma." (PMID 24039782, 2013).
neuroblastoma (continued). "In summary, our findings further support the notion that GRP/GRP-R is a promising therapeutic target in the treatment of clinically aggressive neuroblastomas." (PMID 23468863, 2013). "We have reported that GRP stimulates neuroblastoma cell proliferation and promotes PI3K/AKT-mediated cell survival." (PMID 24039782, 2013). "Gastrin-releasing peptide receptor (GRP-R) overexpression downregulated PTEN transcription and GRP treatment induces neuroblastoma cell cycle progression via PI3K/AKT." (PMID 24039782, 2013). "Given its crucial function in primary neoplasm growth, we sought to determine the role of GRP in neuroblastoma invasion and metastasis." (PMID 24039782, 2013). "Combination therapies using cytotoxic chemotherapeutic agents and GRP antagonists to targeting metastatic disease would be of significance in treating aggressive neuroblastoma in the future." (PMID 24039782, 2013). "We have previously demonstrated an increased expression of GRP and its receptor, GRP-R, in the more aggressive undifferentiated neuroblastoma 13]." (PMID 24039782, 2013). "We next wanted to determine the effects of silencing GRP on neuroblastoma tumor growth and metastasis using our murine metastasis model." (PMID 24039782, 2013). "In this study we have identified that GRP silencing can negatively impact neuroblastoma progression in several ways." (PMID 24039782, 2013). "Previously, we have reported that BBS, an amphibian equivalent of GRP, promotes neuroblastoma tumor growth in vivo, and is an important stimulator of angiogenic pathway." (PMID 23211542, 2012). "GRP/GRP-R regulates neuroblastoma cell growth, transformation and migration by correlative regulation of FAK." (PMID 23211542, 2012). "We reported that the upregulation of GRP-R increases the binding capacity for its ligand GRP, resulting in a faster constitutive neuroblastoma cellular growth rate." (PMID 23211542, 2012). "We reported that an increased GRP and GRP-R expression is found in more undifferentiated neuroblastoma." (PMID 23211542, 2012). "Our results also support for the important role of FAK as a mediator of GRP/GRP-R signaling, and further validate GRP as an inducer of cell migration in neuroblastoma." (PMID 23211542, 2012). "In this study, we provide compelling evidence from cell and animal studies that FAK is an important mediator of GRP/GRP-R signaling-induced neuroblastoma growth and metastasis." (PMID 23211542, 2012). "In conclusion, our study demonstrates that FAK is a crucial regulator of GRP/GRP-R signaling in neuroblastoma." (PMID 23211542, 2012). "Ets-1 expression is stimulated by gastrin-releasing peptide (Grp) that stimulates neuroblastoma growth, and the induction of Ets-1 in these cells promotes the expression and secretion of the angiogenic chemokine interleukin-8." (PMID 20454645, 2010). "GRP stimulates neuroblastoma growth and the expression of angiogenic markers, platelet endothelial cell adhesion molecule-1 and vascular endothelial growth factor expressions." (PMID 19169356, 2009). "The authors proposed that GRP could be a promising candidate tumor marker for malignant retroperitoneal tumors, including neuroblastomas." (PMID 34539578, 2021). "On the other hand, a specific role of autophagy in angiogenesis has been reported in neuroblastoma cells that showed that autophagy is able to suppress angiogenesis through degradation of pro-angiogenesis peptide which is called gastrin-releasing peptide (GRP)." (PMID 34660642, 2021). "In addition, GRP silencing in these neuroblastoma cells increased the expression and accumulation of PTEN in the cytoplasm, where it colocalized with p27, suggesting that p27 was functioning as a tumor suppressor by stabilizing PTEN in the cytoplasm." (PMID 34539578, 2021). "Data from one experimental study raise the possibility that silencing of GRP secreted by neuroblastomas, which can have an autocrine growth effect, could potentiate the use of chemotherapeutic agents." (PMID 34539578, 2021).